HK2 (hexokinase 2)
Diseases named in the same sentence as HK2 in open-access papers (continued):
Sharing a sentence is not in itself a finding about the gene and the disease.
cancer (continued). "Collectively, cancer cells increase glycolysis by upregulating metabolic enzymes, such as HK2, PKM2, and LDHA, to sustain proliferation and survival." (PMID 40734168, 2025). "Hexokinase 2 (HK2), an essential enzyme in glucose metabolism, plays a vital role in facilitating glucose uptake and utilization in cancer cells." (PMID 40124623, 2025). "In HCC, HK2 promotes the survival and proliferation of cancer stem cells by activating ACSL4 and enhancing fatty acid β-oxidation." (PMID 40520908, 2025). "Our data demonstrate that glycolytic HK2 and PKM2 expression were upregulated in cancer cells which emphasized the diet-associated alterations in hepatic metabolism in the context of HCC." (PMID 40076869, 2025). "Among the five human HK isoforms been identified, HK2 is frequently overexpressed in diverse cancer cells and largely absent in normal tissues, making it a promising selective target for cancer therapy." (PMID 40862767, 2025). "Previous studies have demonstrated that AP can suppress the expression of Hk2 and Glut1 mRNA in various cancer cell lines." (PMID 41150773, 2025). "Both STAT3 and HK2 are critical components of the Warburg effect, contributing to altered glucose metabolism in cancer cells." (PMID 39859445, 2025). "Another metabolic intervention lies in glycolysis, where targeting hexokinase 2 (HK2), the rate-limiting enzyme, alters energy metabolism in cancers such as HPV + CC." (PMID 40781676, 2025). "It was found that HK2 and G6PDH were overexpressed in cancer-associated adipose tissue, accompanied by increasing PPP activity." (PMID 39991762, 2025). "Under hypoxic conditions, the interaction between HK2 and TIGAR amplifies HK2 activity, helping regulate mitochondrial ROS levels—further reinforcing HK2's involvement in the progression of cancer." (PMID 40520908, 2025). "HK2 is highly expressed in tumors and plays an important role in promoting the Warburg effect during cancer-related processes, including cancer growth, apoptosis, angiogenesis and metastasis 54-57." (PMID 39990211, 2025). "One such enzyme is HK2, whose overexpression results in increased glycolytic flux—a characteristic feature of cancer cells." (PMID 40956032, 2025). "Among them, HK2 isoenzyme was found to be overexpressed in various cancer types, while HK1 is the predominant isoform in normal cells." (PMID 40941984, 2025). "The activation of CMA increased the degradation of HK2, which triggered the metabolic disorder and impaired proliferation of cancer cells." (PMID 40083922, 2025). "Due to the heightened dependency of cancer cells on glucose, the overexpression of HK2 contributes to meeting the high-energy state required for the rapid proliferation of cancer cells." (PMID 39991762, 2025). "This dual role of HK2 highlights its significance as a therapeutic target, with potential implications for cancer metabolism and immunotherapy." (PMID 40181966, 2025). "This metabolic adaptation, driven by hsa_circ_0069094, aligns with prior research showing the critical role of HK2 in cancer cell metabolism and the reliance of malignant cells on glycolysis to sustain rapid growth." (PMID 40965819, 2025). "HK2 has been shown to be upregulated in aggressive cancers, and our results confirm its increased expression in TAM-R cells relative to TAM-S cells." (PMID 39859445, 2025). "The ADAMTS9-AS2/let-7a-5p/HK2 axis plays an important role in the regulation of cancer metabolism and cell proliferation, which has potential implications for cancer therapy." (PMID 40831535, 2025). "By facilitating the first step in glycolysis, HK2 is responsible for promoting cell transition to the Warburg effect, which allows cancer cell lines to undergo aerobic glycolysis and utilize the metabolic advantages discussed earlier." (PMID 41450919, 2025). "HK2 inhibition disrupts the glycolytic pathway, which is crucial for cancer cell survival and proliferation." (PMID 40243996, 2025).
cancer (continued). "There are four subtypes of HK, namely HK1, HK2, HK3 and HK4, among which HK1 and HK2 play a role as drivers of cancer cell glycolysis." (PMID 39895802, 2025). "As it is both independently and cooperatively activated by HIF1 and Myc, HK2 expression is increased in cancer." (PMID 40956032, 2025). "Taken together, HK2 can provide the energy needed by cancer cells, mediate cell survival, inhibit apoptosis." (PMID 39991762, 2025). "This association with BC malignancy underscores the metabolic adaptations driven by hsa_circ_0069094, echoing prior findings on the role of HK2 in cancer cell metabolism." (PMID 40965819, 2025). "For instance, using HK2 inhibitors can block glycolysis in cancer cells, disrupting their energy production." (PMID 40109854, 2025). "One of the well-known indicators of malignant tumors is enhanced glycolysis (Warburg effect) with increased expression of hexokinase 2 (HK2) and glucose transporter type 1 (GLUT1)." (PMID 41154392, 2025). "By phosphorylating glucose to G6P, HK2 promotes the initiation of the glycolytic pathway, nourishing the energy and biosynthetic substances needed for rapidly proliferating cancer cells 82-84." (PMID 39991762, 2025). "BACH1 also regulates cancer cell metabolism beyond fatty acids, including the production of lactate via hexokinase 2 (HK2)." (PMID 39467637, 2025). "HK is one of the main rate‐controlling steps of cancer glycolysis and HK2 has been proposed as an independent CRC prognostic factor." (PMID 40045444, 2025). "Previous research has shown that HK2 is significantly related to the development of several cancer types." (PMID 41245305, 2025). "Studies showed that inhibition of HK2 suppresses the proliferation of various cancers, for instance, pancreatic ductal adenocarcinoma (PDAC) and colorectal cancer (CRC)." (PMID 40076506, 2025). "It significantly inhibited glycolysis and cancer cell proliferation both in vitro and in vivo with low toxicity by directly targeting HK2." (PMID 40941984, 2025). "TGF-β activates the AKT signaling pathway to enhance HK1 and HK2 expression in cancer cells, leading to increased glucose consumption, ATP production, and precise modulation of cell cycle distribution." (PMID 39895802, 2025). "Seven of the identified HGs (HK2, SRSF10, SOD1, ERO1L, IRF3, MME, and SH3BP5) were associated with PE and various carcinomas." (PMID 40966654, 2025). "This overexpression of HK2 is thought to provide a growth advantage to cancer cells by allowing them to more efficiently utilize glucose for energy and mass production." (PMID 39136001, 2024). "The influence of FTO on cancer metabolism is notable, as it affects the expression levels of HK2 both at the mRNA and protein levels." (PMID 39175477, 2024). "Another factor participating in glucose metabolism, upregulated in cancer cells, is hexokinase 2 (HK2), an enzyme catalyzing the first stage of glycolysis, i.e., the phosphorylation of glucose to glucose-6-phosphate." (PMID 39201656, 2024). "Our investigation additionally reveals that STAT1 plays a role in the transcriptional regulation of HK2, further delineating the complex network of molecular interactions driving cancer metabolism." (PMID 38750462, 2024). "Although less directly involved in fructose metabolism than KHK, HK2’s broad role in phosphorylating hexose sugars underscores its significance in cancer cell metabolism and survival." (PMID 39107723, 2024). "Since cancer cells represent higher glycolytic activity, the inhibition of HK2 activity in cancer cells is actively reflected in the inhibition of 2-NBDG uptake." (PMID 38529190, 2024). "HK2 overexpression has been observed in various types of cancers and targeting HK2 -driven Warburg effect has been suggested as a potential cancer therapeutic strategy." (PMID 38352584, 2024). "Cancer cells often upregulate the expression of key glycolytic enzymes, such as GLUT1, HK2, and MCT1, which are implicated in the mammalian target of rapamycin (mTOR) signaling pathway." (PMID 39479443, 2024).
cancer (continued). "Mechanistically, miR-145 likely induces apoptosis by targeting SUMO-specific peptidase 1 (SENP1)-mediated hexokinase (HK2) SUMOylation and glycolysis pathways and, in turn, sensitizing the cancer cells to CPT." (PMID 39215325, 2024). "In vitro studies showed that HK2 overexpression increases cancer cells’ resistance to chemotherapy and that HK2 downregulation improves the radiosensitivity of TNBC." (PMID 39201646, 2024). "On the other hand, METTL3, a known m6A methyltransferase, plays a contrasting role by enhancing the stability and subsequent protein synthesis of HK2 mRNA, thereby facilitating an increased glycolytic flux essential for cancer cell proliferation and survival." (PMID 39175477, 2024). "Highly glycolytic proliferating cells, such as cancer cells, rely on HK2 expression to accelerate glucose metabolism, even under hypoxemia conditions." (PMID 39192292, 2024). "Collectively, our results further reinforce the concept that HK2 can connect and amplify growth factors signaling with ChREBP-mediating regulation of glucose metabolism to support cell proliferation and cancer development." (PMID 38424041, 2024). "This process inhibits HK2-mediated glucose metabolism and enhances cancer cell sensitization for apoptosis induction." (PMID 38577616, 2024). "Collectively, these results indicated the proof-of-concept for the prototypical lead towards HK2 inhibition with anti-cancer potential." (PMID 38529190, 2024). "HK2 is particularly important in cancer cells, where it is often overexpressed and contributes to the characteristic increased glucose metabolism of many cancer types." (PMID 39136001, 2024). "HK2 overexpression has been reported in several carcinomas, whereas its deletion reportedly reduces cancer cell proliferation." (PMID 38225447, 2024). "In the targeted therapy of cancer, regulators such as hexokinase 2 (HK2), pyruvate kinase M2 (PKM2), enolase 1 (ENO1), and lactate dehydrogenase A (LDHA) are crucial for the glycolytic pathway." (PMID 39484162, 2024). "We also revealed the protein connections between USP14, HK2, and P62 and elucidated the potential mechanisms driving cancer development." (PMID 38383348, 2024). "Among all human hexokinase isoenzymes, HK2 shows overexpression in cancer cells, which makes it interesting in the context of molecularly targeted therapy." (PMID 38338374, 2024). "Hexokinase 2 (HK2) is a pivotal regulator of glycolysis, where aberrant expression is observed in many cancers." (PMID 39713255, 2024). "For example, hexokinase 2 (HK2), which catalyses the first step of glycolysis, is often overexpressed in cancer cells, enhancing glucose uptake and metabolism." (PMID 39601114, 2024). "The increased expression of HK2 in cancer is positively correlated with cancer malignancy, which is regulated by numerous ncRNAs." (PMID 38238756, 2024). "Hexokinase, particularly Hexokinase 2 (HK2), plays a crucial role in aerobic glycolysis in cancer cells by being the initial rate-limiting enzyme in the glycolytic pathway, catalyzing the phosphorylation of glucose to glucose-6-phosphate." (PMID 39408832, 2024). "For instance, several compounds, including Glycyrrhizin, Licochalcone A and σ-tocotrienol, have been successfully used to suppress cancer cell proliferation by decreasing HK2 expression via AKT signaling." (PMID 39339236, 2024). "Its mechanism of action is largely based on the impairment of the cancer cell energy metabolism by inhibiting HK2 (Hexokinase 2) and GAPDH (Glyceraldehyde 3-phosphate dehydrogenase) resulting in ATP reduction." (PMID 39061250, 2024).
cancer (continued). "In summary, while both FaDu and Cal27 cells exhibit elevated HK2 expression levels characteristic of cancer cells, their response to HK2 inhibitors differ significantly." (PMID 38529190, 2024). "Several studies have confirmed that GLUT1, HK1 and HK2 expression is closely related to the progression of malignant tumors." (PMID 38514913, 2024). "The β-catenin-mediated activation of glycolytic proteins leads to the activation of c-Myc, and, consequently, c-Myc upregulates the band level of PKM2, LDHA, and HK2 in cancer cells." (PMID 39273365, 2024). "Li also discovered that the SBD domain of HSP70 induces mitochondrial expression of HK2 to increase mitochondrial membrane potential, consequently promoting cisplatin resistance and apoptosis resistance in cancer cells." (PMID 38577616, 2024). "HK2 contributes to the glycolytic pathway and interacts with mitochondrial proteins to prevent apoptosis, promoting cancer cell survival." (PMID 39107723, 2024). "After validating the anti-cancer potential of the HK2 inhibitors, mechanistic studies were carried out employing H2 in the relatively sensitive Cal27 cell line." (PMID 38529190, 2024). "The pursuit of small molecule inhibitors targeting hexokinase 2 (HK2) has significantly captivated the field of cancer drug discovery." (PMID 38529190, 2024). "Some studies have reported that HK2 has great advantages as a therapeutic target for cancer; however, HK2 has limitations as a therapeutic target due to its widespread expression in all organs." (PMID 38041756, 2024). "Collectively, these results demonstrate that HK2 can connect and amplify both growth factors signaling with ChREBP-mediated glucose metabolic reprogramming to support cell proliferation and cancer development." (PMID 38424041, 2024). "In this context, the phosphorylation of IkBα is catalyzed by hexokinase-2 (HK2), a glycolytic enzyme that was found overexpressed in numerous types of cancer." (PMID 39139809, 2024). "In vitro and in vivo studies have shown that, compared to HK1, HK2 is highly expressed in cancers, particularly in highly glycolytic cancers, as HK2 can partially enhance glucose flux." (PMID 38538285, 2024). "Elucidating the role of HK2 in tumorigenesis and chemotherapy resistance would facilitate the identification of novel anti-cancer therapeutic strategies." (PMID 38577616, 2024). "HK2’s role in cancer is well-documented, with high expression levels correlating with poor prognosis in various cancers." (PMID 39107723, 2024). "As both AMPK and HK2 are the main enhancers of glucose uptake and glycolysis in cells, this phenomenon leads to increased FDG uptake in cancer-associated adipocytes." (PMID 39338206, 2024). "In cancer cells, the expression of hexokinase 2 (HK2) is induced alongside the hexokinase 1 (HK1) that is also present in normal cells, thereby doubling the capacity for this critical step." (PMID 39479443, 2024). "HK2 is crucial in regulating glycolysis and is overexpressed in different types of cancer, which can alter intracellular glucose homeostasis." (PMID 38234430, 2023). "Although BIS directly stabilizes hexokinase 2 mRNA and glutaminase in cancer cells, the molecular mechanism of defective energy metabolism under BIS depletion is unclear." (PMID 37298584, 2023). "A link between cisplatin resistance and HK2 expression has been observed in ovarian and cervical cancer models." (PMID 36765947, 2023). "Cisplatin interacted with GSH and regulated ROS homeostasis.Cisplatin redirected the cancer cells from the aerobic glycolysis to oxidative phosphorylation.Cisplatin downregulated HK2 and PDK." (PMID 37110218, 2023). "A growing number of studies have shown that targeting HK2 effectively controls glucose metabolism and influences cancer progression." (PMID 37204526, 2023).
cancer (continued). "The efficacy of targeting HK2 has also been well characterized in cancers that can give rise to SPCs." (PMID 37233659, 2023). "In cancer, membrane-bound HK2 increases consumption of glucose and production of lactate to increase proliferation and resistance to apoptosis induced from chemotherapy." (PMID 37529037, 2023). "HK2 has been identified as a key participant in the Warburg effect and put forward as a metabolic target for cancer therapy owing to its solid position as a major isoenzyme that is overexpressed in tumors." (PMID 37208722, 2023). "Hexokinase 2 (HK2), a critical rate-limiting enzyme in the glycolytic pathway catalyzing hexose phosphorylation, is overexpressed in multiple human cancers and associated with poor clinicopathological features." (PMID 37019900, 2023). "It has been previously reported that HK2 inhibitor-3-BrPA possessed profound anti-cancer properties by alkylating the active sites of HK253." (PMID 37497007, 2023). "In particular, miRNAs have been shown to exhibit a regulatory effect on glucose metabolism in cancer by inhibiting HK2." (PMID 37019900, 2023). "In most cancer tissues, the expression of the HK family, especially HK2, is significantly increased." (PMID 36994237, 2023). "High expression of HK2 in cancer cells and its complex regulatory network directly promote an increase in the aerobic glycolysis level of cancer cells, which fulfills the energy demand of rapidly proliferating cells." (PMID 36994237, 2023). "As a member of hexokinase, HK2 is located on the outer membrane of mitochondria and has been shown to be upregulated in cancers." (PMID 36950803, 2023). "Several drugs have shown to dissociate HK2 from mitochondria; among them, MJ is a plant stress hormone shown to dissociate HK2 from mitochondria in cancer cells as well as suppress proliferation and induce cell death." (PMID 37529037, 2023). "3‐Bromopyruvic acid, a pyruvate analogue, is another plausible HK2 inhibitor, which has been shown to induce apoptosis and inhibit proliferation in a range of cancer types." (PMID 38034101, 2023). "This happens in KRAS mutant cancer, where hexokinase 2 (HK2) overexpression has been shown to be a key player to divert glucose in ribonucleotide and fatty acids synthesis." (PMID 37180110, 2023). "Lonidamine, another inhibitor of HK2 was administered in clinical trials for the treatment of several types of cancer including ovarian, lung, and breast cancer." (PMID 38139462, 2023). "Less is known about HK2 expression in TNBC cells, although HK2 is often upregulated in other human cancers and drives their reprogramming to aerobic glycolysis." (PMID 37915591, 2023). "This is in line with the evidence that overexpression of HK2 in cancer cells confers resistance to apoptosis." (PMID 36984785, 2023). "Most cancers shift their HK expression profiles in favor of HK2, a consequence of metabolic re-programming in cancer." (PMID 37109475, 2023). "A specific inhibitor of HK2, 3BP, showed a promising effect against various cancer models but possessed cross-reactivity with other pyruvylated proteins." (PMID 37762231, 2023). "miR-155 can inhibit the expression of miR-143 by targeting CCAAT enhancer binding protein β (C/EBPβ), resulting in upregulation of HK2 level and promotion of glucose metabolism in cancer cells." (PMID 37204526, 2023). "For example, 2-deoxy-glucose (2-DG), which can inhibit HK2, decreases glycolysis and induces apoptosis in cancer cells." (PMID 37833332, 2023). "HIF-1α is closely related to aerobic glycolysis in cancer, mainly by regulating HK2 and GLUT1 to participate in cancer cell metabolism and accelerate the Warburg effect." (PMID 37204526, 2023). "Increased mitochondria-bound HK2activity exerts protective roles against oxidant-induced programmed cell death, implying that elevated activity of HK2 contributes to avoiding programmed cell death in cancer cells." (PMID 36984785, 2023).